BRAF (B-Raf proto-oncogene, serine/threonine kinase)
Diseases named in the same sentence as BRAF in open-access papers (continued):
Sharing a sentence is not in itself a finding about the gene and the disease.
melanoma (continued). "We showed the value of metabolic analysis by imaging a series of patient-derived, BRAF mutant melanoma cell lines, representing different de-differentiation phenotypes." (PMID 32973134, 2020). "Our study aims to evaluate and review other studies that present the frequency of mutations of BRAF, NRAS, and KIT genes for different populations, and analyse correlation to their clinical-pathological characteristics and to the demographics of melanoma." (PMID 31274706, 2020). "In melanoma, NRAS and BRAF mutations have also been detected and used as genetic markers in tools integrating genetic and morphologic features to improve classification." (PMID 32847629, 2020). "Towards this goal we first identified a novel oncosuppressor miRNA, miR-579-3p, as a novel master regulator of MAPKi resistance in BRAF-mutant melanoma patients." (PMID 32178301, 2020). "Multiple somatic driver mutations were identified, all previously associated with the tumor type in which the mutation was identified, such as BRAF (c.1799T > A, p.Val600Glu) in CRC and melanoma, and PIK3CA (c.1624G > A, p.Glu542Lys) in breast cancer." (PMID 33258446, 2020). "In particular, various combinations with HDAC inhibitor romidepsin were predicted to be effective against BRAF-mutants melanoma cell line MALME-3M, which also held true in the experimental settings." (PMID 33262326, 2020). "For example, following BRAF inhibitor therapy in BRAF V600 mutant melanoma, individual tumors were found to develop multiple resistance events, including NRAS and MEK1 mutations in one patient and two distinct NRAS mutations in another." (PMID 32143590, 2020). "Melanoma cells can adapt to the drugs through phenotypic switching (plasticity), which results in resistance to targeted therapies such as BRAF and MEK inhibitors." (PMID 32626712, 2020). "Comparably, the FDA approved ipilimumab for metastatic melanoma and, in addition, vemurafenib (Zelboraf, Roche), a BRAF serine-threonine kinase inhibitor, and peginterferon alfa-2b (Sylatron) for the therapy of melanoma." (PMID 33297561, 2020). "In a recent study using melanoma PDXs, the group of J.C. Marine revealed that, during the minimal residual disease phase induced by treatment with BRAF/MEK inhibitors, distinct drug tolerant transcriptional states coexist." (PMID 33291749, 2020). "To identify drugs that suppress SPP1 in melanoma, we performed a pilot screening using vemurafenib (BRAF inhibitor), trametinib (MEK inhibitor), and NHWD-870 (BET inhibitor) and found that NHWD-870 inhibited SPP1 expression." (PMID 33052224, 2020). "Further work involving lipid transporters such as CD36 or FATP is required to assess if this dependency in BRAF-mutant melanoma is based on lipid uptake or biogenesis processes." (PMID 31819183, 2020). "We found that Ole potentiates the cytotoxic effect of everolimus against BRAF melanoma cells inhibiting pAKT/mTOR pathway, as measured by the decrease of pAKT/S6." (PMID 32013090, 2020). "Most melanoma patients in Indonesia cannot afford the price of completing a whole cycle of BRAF inhibitor therapy." (PMID 32188503, 2020). "It is also responsible for recruitment of MDSC as restoration of these cells is observed in melanomas resistant to BRAF/MEK inhibitors." (PMID 32517213, 2020). "Although the first description in melanoma of a mutual exclusivity of NRAS and BRAF mutations, more recent studies have shown that their co‐occurrence was possible in the same tumor before treatment." (PMID 35847743, 2020). "A constitutive activation of BRAF, mostly due to the substitution of valine by glutamic acid at position 600 (also known as V600E), affects about 50% of melanoma patients." (PMID 32858889, 2020). "In BRAF-mutant melanomas, uncontrolled MAPK activation leads to an increased production of different ILs and VEGF that influence the activity of the immune system toward a protumor condition." (PMID 33036192, 2020).
melanoma (continued). "Treatment of advanced melanoma has dramatically improved in recent years, and currently include targeted therapies against BRAF or MEK, and immunotherapy." (PMID 32513939, 2020). "In BRAF/NRAS, wild-type melanomas and the mutations or amplifications of the c-KIT gene must be analyzed." (PMID 32054005, 2020). "More recently, the results of clinical phase III studies conducted in the adjuvant setting led to the combined administration of BRAF and MEK inhibitors also in patients with resected high-risk melanoma (stage III)." (PMID 32695793, 2020). "In our assay using BRAF mutant melanoma cells, 4 active compounds were identified that up-regulated the antigen, gp100 and the master regulator MITF." (PMID 32231230, 2020). "We showed that COX2 and PTGES are both overexpressed in several BRAF/MEKi-resistant melanoma cells and tumor tissues, and that COX2 knockdown significantly enhanced drug effects in melanoma cell." (PMID 32967672, 2020). "The efficacy of kinase targeted therapy in patients with melanoma is influenced by B-Raf proto-oncogene, serine/threonine kinase (BRAF) and KIT proto-oncogene, receptor tyrosine kinase (KIT) mutations." (PMID 32260071, 2020). "Among these cases, 21 acral melanoma samples (18.8%) showed positive BRAF V600E staining, and of those, 11 samples (9.8%) showed a heterogeneous staining pattern, with a mixture of VE1-positive and VE1-negative cells." (PMID 32143442, 2020). "Upon further characterization, it was demonstrated that SBI-756 impaired eIF4F complex formation in melanoma cells and inhibited the growth of BRAF, NRAS, and NF1-mutant melanoma cell lines." (PMID 32517051, 2020). "We treated BRAF mutant (A375 and SK-MEL-28) and BRAF wild type MEWO melanoma cells with specific inhibitors of JNK (SP600125), NF-κB (BAY11-7082) and p38 (SB203580 and SB202190)." (PMID 32414111, 2020). "Here, we combined a conditional knockout of Coronin 1C with a genetically engineered mouse model of PTEN/BRAF-driven melanoma." (PMID 32686704, 2020). "Thirdly, BRAF inhibitors enhance the recognition of melanoma cells by the immune system and so reduce the likelihood of the tumour escaping recognition by T cells." (PMID 32645969, 2020). "The use of ErbB3/ErbB2 antibodies restores the cytotoxic activity of these drugs in BRAF-mutant melanoma cell lines." (PMID 33036192, 2020). "These mutations are oncogenic drivers that cause tumor progression and metastasis, and their discovery led to the development of small molecule inhibitors of BRAF, including vemurafenib, dabrafenib and encorafenib, for the treatment of melanoma." (PMID 33003483, 2020). "The aims of this study were to standardize a highly sensitive methodology of digital PCR (dPCR) to accurately identify hotspot mutations in BRAF, NRAS, and TERT in plasma and interrogate its feasibility as a liquid biopsy tool for melanoma patients." (PMID 33122747, 2020). "Our findings reveal genes contributing to resistance to a selective BRAF inhibitor PLX4720, providing new insights into gene regulation in BRAF inhibitor resistant melanoma cells." (PMID 32413516, 2020). "For example, in melanoma, resistance against BRAF-inhibitor was accompanied by increased ECM levels of versican and biglycan." (PMID 33330449, 2020). "The BRAF oncogenic signaling is a prime therapeutic target in melanoma, and small molecule BRAF inhibitors dabrafenib and vemurafenib have been approved for clinical use." (PMID 32531927, 2020). "In this review, we focused on studies reporting the mechanism through which essential oils exert antitumor action in preclinical wild type or mutant BRAF melanoma models." (PMID 32948083, 2020). "Here, we showed that the genetic inhibition of histone acetyltransferase 1 (HAT1) in BRAF-mutant melanoma cells resulted in BRAFi resistance." (PMID 32371878, 2020). "In melanoma with RAS and BRAF mutations autophagy and lysosomal functions are often deregulated to promote cell survival." (PMID 32414111, 2020).
melanoma (continued). "Glycolysis has emerged as a key feature of the BRAF inhibitor response in melanoma cells, and importantly, the metabolic response to vemurafenib in melanoma patients can predict patient outcome." (PMID 33046726, 2020). "Targeted BRAF inhibition therapy (such as vemurafenib and dabrafenib) improved overall survival of melanoma patients with limited durable responses and high relapse rate (50%)." (PMID 32059541, 2020). "Altogether, our data highlight heterogeneity in metabolic adaptations during acquired resistance to vemurafenib in BRAF-mutant melanoma, potentially uncovering key clinically-relevant mechanisms for combinatorial therapeutic targeting." (PMID 31819183, 2020). "Inhibition of the MAPK pathway with BRAF/MEK inhibitors induces the opposite reprogramming in human melanoma cells." (PMID 32759677, 2020). "In the KEYNOTE-022 phase-2 study (NCT02130466), 120 treatment-naive BRAF-V600E/K-mutant patients with advanced melanoma were randomized to receive the BRAF inhibitor dabrafenib and the MEK inhibitor trametinib in combination with pembrolizumab or placebo." (PMID 31947592, 2020). "Here, we have presented valuable real data on the implementation of a commercial and validated test with European conformity in vitro diagnostic for multiple molecular-targeted therapies, including BRAF, in a Spanish cohort of advanced melanoma." (PMID 36046072, 2020). "Once LNPs were obtained with optimal technological characteristics in terms of size and miRNA encapsulation efficiency, we started to determine their biological efficacy in two different BRAF-mutant melanoma cell lines in vitro, namely A375 and M14." (PMID 32178301, 2020). "The treatment of BRAF-mutant melanomas with MAP kinase (MAPK) pathway inhibitors is paradigmatic in precision cancer therapy but also highlights the problem of drug resistance, which limits the benefit to patients." (PMID 32708687, 2020). "In the present study, we depict for the first time a role of miR-146a in controlling BRAF/MEKi resistance in melanoma cells, through a mechanism involving COX2." (PMID 32967672, 2020). "In line with this, other investigational compounds have reached the clinical setting, including B-RAF or MEK inhibitors in BRAF (V600E)-mutant tumors such as melanoma or non-small cell lung cancer." (PMID 33261142, 2020). "This was confirmed in two distinct melanoma cell lines, where we found that Galectin-1 was driving the refractoriness to BRAF-targeted therapy." (PMID 32784465, 2020). "Roesch and colleagues identified another intrinsic resistance mechanism in BRAF V600E mediated malignant melanoma mediated by altered histone modifications." (PMID 32046099, 2020). "Mutations in RAS can lead to activation of the receptor tyrosine kinase-MAPK pathway in cancer development and BRAF dysregulation which occurs in melanoma progression and shows a strong correlation with melanoma metastasis." (PMID 32462000, 2020). "We also showed that PMCA4b overexpression inhibited migration in vitro and metastatic activity in vivo of BRAF mutant melanoma cells." (PMID 32414111, 2020). "To study further the degradation pathway of PMCA4b in BRAF mutant melanoma cells we examined its distribution between the different endocytic compartments using specific markers of the endo/lysosomal system." (PMID 32414111, 2020). "For example, we found that responses to the BRAF-inhibitor dabrafenib showed substantial variation, even among the highly sensitive BRAF-mutant melanoma cell lines." (PMID 32855387, 2020). "Specifically, TM blunted S6 phosphorylation in both BRAFV600E and BRAF wildtype (WT) melanoma cell lines." (PMID 32085796, 2020).
melanoma (continued). "Growing evidence suggests that BRAF inhibitors, in addition to their direct anti-tumor activity, can also promote immune responses to melanoma." (PMID 32708268, 2020). "In the same line, fibroblast-secreted HGF activates both the MAPK and PI3K/AKT pathways contributing to BRAF-targeted therapies' primary resistance in melanoma and in a subset of colorectal and glioblastoma cancer cells." (PMID 33553157, 2020). "With the advent of targeted therapy in melanoma, namely, BRAF kinase inhibitors for BRAF mutant tumors, epigenetic studies emerged focusing on the processes that underlie therapy resistance." (PMID 32185171, 2020). "Here, we identified the miR-146a/COX2 axis as playing a critical role in the mechanisms sustaining melanoma resistance; thus, this axis represents a druggable signaling pathway for improving the effects of BRAF/MEKi therapy in melanoma patients." (PMID 32967672, 2020). "For instance, mutations of BRAF and NRAS target the mitogen-activated protein kinase (MAPK) pathway which is disorderly regulated in almost all melanomas." (PMID 33136551, 2020). "In melanoma BRAF inhibition combined with drugs that target oxidative metabolism can lead to improvement in disease outcomes." (PMID 32509589, 2020). "We conclude that dysregulation of CDK6 by JUN mediates resistance to BRAF inhibition in melanoma cells." (PMID 32413516, 2020). "Continuous BRAF inhibition of BRAF mutant melanomas is known to induce a series of phenotypic changes in the cancer cells that result in therapy resistance and escape from immune control before genetic fixation of the acquired resistant state." (PMID 33322354, 2020). "Different studies have linked mutually exclusive mutations in the BRAF, NRAS, C-KIT, and NF-1 genes with the development of melanoma." (PMID 32775409, 2020). "Actually, the first-line therapeutic approach for advanced melanoma consists in immunotherapy with anti-PD1 antibodies or targeted therapy with BRAF and MEK inhibitors." (PMID 32671117, 2020). "The use of TKIs has shown a significant improvement of patient overall survival and the combinations therapy with BRAF/MEK inhibitors is now accepted as the standard care for BRAF-muted advanced melanoma." (PMID 33050185, 2020). "The enhanced autophagic-lysosomal activity of BRAF-resistant melanoma cells exacerbates adenosine triphosphate (ATP) secretion, which in turn increases melanoma cell invasion." (PMID 33003483, 2020). "Signaling through the DUSP6-ERK5 pathway is modulated by MIR211 in BRAFV600E driven melanoma tumors, and this function is involved in the resistance of tumor cells to the BRAF inhibitor, Vemurafenib." (PMID 33628737, 2020). "A mutation in BRAF (BRAF V600E) affects various signaling pathways, including mitogen activated protein kinase (MAPK) and PI3K/AKT/mammalian target of rapamycin (mTOR) in melanoma." (PMID 32626712, 2020). "We here report a tumor-suppressive role of miR-146a in BRAF/MEKi-resistant melanoma and demonstrate that the manipulation of miR-146a/COX2/PGE2 axis can restore BRAF/MEKi chemosensitivity." (PMID 32967672, 2020). "In our previous study, we found that PMCA4b expression was downregulated in BRAF mutant melanoma cell lines and inhibition of the Ras-BRAF-MEK-ERK pathway markedly increased it at both the mRNA and protein levels." (PMID 32414111, 2020). "Preclinical studies have successfully targeted PI3K signalling in combination with BRAF/MEK inhibitors in BRAFV600E-mutated colorectal cancer and melanoma cells." (PMID 32411231, 2020). "Patients with melanoma treated with a BRAF inhibitor have also demonstrated enhanced antigen expression in tumors." (PMID 32260561, 2020). "Mutations leading to an increase in PI3K/AKT pathway activity have been identified in 22% of melanomas with acquired resistance to BRAF inhibitors." (PMID 32605090, 2020). "miR-125b-5p were shown to be involved in the vemurafenib resistance of resistant BRAF-mutant melanoma cell." (PMID 32466797, 2020).
melanoma (continued). "Remodeled ECM leads to adhesion-dependent (integrin and focal adhesion-dependent) signaling to ERK that negates the effect of BRAF inhibition in the melanoma cells." (PMID 33212834, 2020). "V600E mutation is clinically relevant, because based on its presence, many patients receive targeted therapy, although paradoxically, BRAF V600E has been reported to be more frequent in benign (≈80%) than in dysplastic nevi (≈60%) or melanoma (≈40%-45%)." (PMID 32168325, 2020). "BRAF inhibitors have proven to be highly effective in targeting the oncogenic BRAF protein in melanoma patients." (PMID 32858528, 2020). "Using this model, we found strong inhibition of A375 melanoma cell metastatic activity in response to p38 and BRAF inhibitor treatments." (PMID 32414111, 2020). "HRAS mutations were found at a higher frequency in CSCC lesions arising in melanoma patients treated with BRAF-inhibition." (PMID 32331425, 2020). "The discovery and characterisation of the molecular underpinnings of melanoma have exposed novel potential therapeutic targets, BRAF being one of the most relevant." (PMID 31819183, 2020). "Altogether, our data suggest that co-targeting of BRD/BET proteins in concert with BRAF/MEK inhibitors is likely to promote more durable responses of targeted therapy for BRAF-mutant melanoma in vivo." (PMID 31932756, 2020). "In this study, aPD‐1 was associated with improved outcomes, including OS, rwPFS, DOR, and TTNT, following 1L initiation among patients with BRAF‐mutant advanced melanoma compared to BRAF/MEKi." (PMID 32871054, 2020). "Taken together, these results indicate that transcriptional PD‐L1 induction in melanoma cells is driven by IFN‐γ and can be specifically decreased in BRAF‐mutated cells by inhibition of this kinase." (PMID 32330348, 2020). "We then describe the main functional properties of myofibroblasts in wound healing and fibrosis and how melanoma cells can highjack some of them under BRAF and MEK inhibitor treatment." (PMID 32466585, 2020). "Recently, RASA2 and NRAS mutations were confirmed to be mutually exclusive, with NF1 mutations significantly co-occurring with RASA2 mutations in BRAF and NRAS wild-type melanomas, since RASA2 inhibits NRAS and NF1 inhibits KRAS and HRAS." (PMID 32850962, 2020). "For our BRAF-V600E melanoma in vivo model, we needed to utilize higher doses and/or increase the frequency of administration for these compounds to achieve similar results—i.e., a reduction in cell viability in vitro and inhibition of tumor growth in vivo." (PMID 32764384, 2020). "Low glutamine levels in the core of a melanoma induce histone hypermethylation and BRAF inhibitor resistance." (PMID 33003483, 2020). "Fourth, a combination treatment with phendione and BRAF inhibitor prevents the emergence of acquired resistance to BRAF inhibition in a PDX model of melanoma." (PMID 32241802, 2020). "Of the four patients that progressed on BRAF inhibitor therapy (MM321, MM337, MM302 and MM358), all PDXCs demonstrated resistance to vemurafenib in HTDS, when compared with the three previously untreated BRAF-mutant melanoma lines (MM313, MM314 and MM325)." (PMID 31857724, 2020). "In melanoma or NSCLC, specific inhibitors of BRAF kinase Vemurafenib and Dabrafenib and MEK inhibitors Binimetinib and Trametinib are used only in BRAF-mutated tumors." (PMID 32111026, 2020). "It is widely described that HGF confers resistance to the BRAF inhibitor Vemurafenib in BRAF-mutant melanoma cells." (PMID 33003469, 2020). "Activation of NFkB signaling, along with low expression and activity of MITF, represent hallmarks of melanoma resistance to targeted therapy, predictive of poor prognosis for patients treated with BRAF/MEKi." (PMID 32967672, 2020). "The current therapies for advanced stage disease in melanoma are based on the inhibition of either the aberrantly activated BRAF/MEK pathway, or the immune checkpoints PD1 and CTLA4." (PMID 33193402, 2020).